CXCL10 (C-X-C motif chemokine ligand 10)
Diseases named in the same sentence as CXCL10 in open-access papers (continued):
Sharing a sentence is not in itself a finding about the gene and the disease.
cancer (continued). "The analysis results showed that Macrophages_FABP4 exhibited significant depletion in cancer tissues, while Macrophages_SLENOP, Macrophages_SPP1, Macrophages-STMN1, and Macrophages_CXCL10 showed significant enrichment." (PMID 40916017, 2025). "When CXCL10 binds to its receptor CXCR3 on ‎cancer cells or immune cells, it can activate the MAPK/ERK signaling pathway, leading to various ‎cancer-related processes." (PMID 40760734, 2025). "Several cell types within the TME, including both immune and cancer cells, are significant producers of the chemokines CCL5 and CXCL10." (PMID 40248897, 2025). "Previous studies have demonstrated robust cancer-induced systemic changes, characterized by elevated inflammatory mediators such as IL-6, TNF-α, CXCL10, and MMP9." (PMID 41153795, 2025). "Elevated circulating levels of 6 cytokines (PD-L1, CXCL10, HGF, CCL2, MIG, and IL-6) were observed in cancer patients compared with that in healthy volunteers." (PMID 38776028, 2024). "CXCL10 and its corresponding receptor CXCR3 are highly expressed by various cell types, including leukocytes and macrophages as well as some epithelial and cancer cells in a wide range of human disorders." (PMID 39268223, 2024). "Among chemokines, especially CCL4, CCL5, CCL8, CXCL9, CXCL10 and CXCL11 were markedly positive correlated with LAMP3 expression in most cancers." (PMID 38146591, 2024). "Seven chemokines (CCL18, CCL8, CXCL9, CXCL10, CXCL11, CCL26, and CCL7) showed positive relations in more than 25 cancer types." (PMID 38655053, 2024). "In this study, we demonstrated significantly higher levels of circulating PD-L1, CXCL10, MIG, HGF, CCL-2, and IL-6 in cancer patients compared to normal healthy subjects." (PMID 38776028, 2024). "High IDO1 expression often co-segregated with high expression of immune checkpoints across cancers and there was an independent, statistically significant, and linear relationship between IDO1 expression and that of PD-L1, STAT1, and CXCL10 transcripts." (PMID 38632994, 2024). "WDR43 different expression levels in various cancers were positively correlated with chemokines, including C-X-C motif chemokine ligand (CXCL) 9, CXCL10, and CXCL11." (PMID 39093744, 2024). "The levels of circulating PD-L1, CXCL10, MIG, HGF, CCL-2, and IL-6 were significantly higher in the cancer group compared with those of the control group." (PMID 38776028, 2024). "As a secreted chemokine, C-X-C motif Chemokine Ligand 10 (CXCL10) is primarily produced by fibroblasts, cancer cells, endothelial cells, and monocytes in response to IFN-γ secretion." (PMID 38720149, 2024). "VPS34 inhibition in cancer cells triggers activation of the cGAS–STING pathway and thereby induces a type I interferon response leading to CCL5/CXCL10 chemokine secretion." (PMID 38506049, 2024). "In murine cancer cell lines B16F10 and 4T1, TH1579 treatment at 1 μM for 24 h resulted in increased transcription of Ccl5 and Cxcl10." (PMID 38796460, 2024). "For example, in small cell lung cancer (SCLC), a WEE1 inhibitor induced DNA damage in cancer cells, increasing type I interferons, CCL5 and CXCL10 via activation of the cGAS-STING pathway, enhancing the response to PD-L1 blockade." (PMID 38796460, 2024). "In specific, TIS is referred to as an 18‐gene signature (CCL5, GZMK, CD3D, CD3E, CD2, HLA‐DRA, IL2RG, NKG7, CIITA, CXCR6, LAG3, TAGAP, HLA‐E, CXCL13, IDO1, CXCL10, STAT1, and GZMB), which was related to the response to ICIs in various cancers." (PMID 37434432, 2023). "The IFN-β, CXCL10, and IL-6 expression in MTHMS + L group elevated significantly both in cancer cells and BMDCs, evidencing the effective cGAS-STING pathway activation." (PMID 37221157, 2023). "Specifically, chemokines such as CXCL9, CXCL10, and CXCL11 and chemokine receptors such as CXCR5, CCR4, CCR8, and CCR1 were positively correlated with IGF2BP3 expression in various cancer types." (PMID 36761737, 2023).
cancer (continued). "Two discovery pan-cancer datasets were used to examine the 4-chemokine signature (CCL4, CCL5, CXCL9, CXCL10; herein referred to as c-Score) as a predictive biomarker for T cell-inflammation and ICI treatment outcomes across different solid tumor types." (PMID 37558751, 2023). "QUE’s anti-inflammatory properties were also confirmed by the potent downregulation of pro-inflammatory chemokines, in particular the CXCR3 ligands CXCL9, CXCL10, and CXCL11, which are important players in chronic liver diseases, inflammation, and cancer." (PMID 37755981, 2023). "So, the levels of IFN-β, C-X-C motif chemokine 10 (CXCL10), and IL-6 in cancer cells after various treatments and bone marrow-derived dendritic cells (BMDCs) incubated with pretreated cancer cells were measured." (PMID 37221157, 2023). "For example, the MHC class and CD274 work in cancer and immune cells, and CCL5, CXCL10 and IFNB1 are downstream of ISRE and induce immune cell infiltration into cancer tissue." (PMID 37543704, 2023). "In terms of gene expression, SPP1, IKBKE, CXCL11, CXCL10, and other genes showed extensive high expression in COAD, ESCA, KIRC, READ, UCEC, and other cancers." (PMID 37666853, 2023). "IFN-γ promotes migration of immune cells to TME by transcriptionally regulating the expression and secretion of CXCL9, CXCL10 and CXCL11 and their cognate receptor CXCR3 in T cells, NK cells, monocytes, DCs and cancer cells." (PMID 37646041, 2023). "Reports have asserted that the CXCL9, CXCL10, and CXCL11 axes are important for immune activation in cancer therapy." (PMID 37048082, 2023). "V-Navo@gel treatment induced the expression of chemokines in cancer cells, including CCL2, CXCL10 and CXCL11 that drive the generation and recruitment of T cells, B cells and myeloid-derived cells." (PMID 37296221, 2023). "ANK2-MT LUAD was characterized by high expression of chemokines (CXCL9, CXCL10, CXCL11, and CXCR3) involved in the recruitment of anti-cancer immune cells." (PMID 36539782, 2022). "qPCR was performed for the treated murine 4T1, LLC, and CT26 cancer cell lines, and the data showed that the total expression levels of CCL5, CXCL9, and CXCL10 were significantly increased after tucidinostat treatment." (PMID 36352411, 2022). "CXCL10 and CCL5 are chemokines that induce antitumor immunity in SCLC and other cancer types in response to type I IFNs." (PMID 35584676, 2022). "The influence of CXCL10 and STAT2 expression on patient survival has been reported in several human cancers." (PMID 35207629, 2022). "The ACK1 kinase not only suppressed T-cell activation but also a key chemokine, CXCL10, which plays a crucial role in directing the migratory properties and potentiation of CD4+ and CD8+ T cells in the context of cancer and inflammatory autoimmunity." (PMID 36376335, 2022). "These include: CDH1, MUC1, THBS4, and MSLN for PEs related to cancer; ADA2, CXCL10, and WARS for TB-PEs; CRP, S100A9, and VIM for parapneumonic PEs; and C9, LDHA, HPX, LDHB, and C3 for benign-PEs." (PMID 35197508, 2022). "Some of these factors were exclusive to CAFs (mainly CXCL10 and CXCL12), others to cancer cells (mainly CXCL7 and CCL20), and some factors, such as CCL2, were common to both cell types." (PMID 35192545, 2022). "Metastasis is the prominent feature of advanced cancers, and NEIL3 was correlated with many metastasis-inducing chemokines, such as CXCL10, which confirms our previous result that NEIL3 is related to an advanced stage and poorer prognosis in cancers." (PMID 36612106, 2022). "Pro-tumor chemokines, such as CXCL8, CXCL9, CXCL10, and CXCL11, can promote cancer cell proliferation and metastasis, and our results revealed that NEIL3 expression was positively correlated with them." (PMID 36612106, 2022). "We observed that immunostimulatory chemokines such as CXCL9, CXCL10, CXCL11, CCL4, and CCL5 were consistently down‐regulated for the tumors with high Hh activity across the 14 cancer types." (PMID 34841742, 2022).
cancer (continued). "It was worth noting that the expression levels of CXCR4, PPP3R1, HSP90AB1, CXCL10, and S100A12 were substantially elevated in multiple types of cancer tissues." (PMID 36569892, 2022). "CXCL10 and CXCL11 were predominantly synthesized and produced by monocytes, endothelial cells, fibroblasts, and cancer cells under the induction of IFN-γ and TNFα." (PMID 36003333, 2022). "Here, we found an overall upregulated expression pattern of CXCL10 and TMPRSS2 compared to a normal state depending on the individual stages of cancer and different age groups." (PMID 36239108, 2022). "This team has demonstrated that macrophages differentiated in the presence of pancreatic tumor cells (PANC1 and PT45) and treated with Poly (I:C) secrete more CXCL10 and CCL5 which trigger the cytotoxic activity of TC-Mφ against cancer cells." (PMID 33402730, 2022). "Among them, CXCL9, CXCL10, and CXCL11 have been reported to promote cancer cell proliferation by combining with CXCR3A." (PMID 35992864, 2022). "CXCL10, CXCL9, CXCL11/CXCR3 is an important axis for immune activation, which is necessary for developing novel cancer therapy." (PMID 36685901, 2022). "Knockdown of NANOG or HDAC1 with a siRNA robustly dampened expression of the effectors of NANOG signaling, such as CXCL10 and MCL1, across all tested cancer cells." (PMID 35104240, 2022). "The current findings showed that the expressions of multiple immune-related genes, including CXCL9, CXCL10, GZMB, and PDCD1LG2, were upregulated in cancer with high TME scores." (PMID 35242245, 2022). "CXCL9, CXCL10, CXCL11, CXC12, CXCL13, and CXCL14 expression in the tissue adjacent to carcinoma was significantly different." (PMID 35181719, 2022). "The two key open-end questions are which human cancer to treat, and which of them CXCL9 would be favored over CXCL10, and when CXCL10 would be used as a lead molecule over CXCL9?" (PMID 34944943, 2021). "For drug sensitivity analysis, we assessed the correlation between CXCL10 expression and IC50 values of molecules from the Cancer Drug Sensitivity Genomics (GDSC) database." (PMID 33345267, 2021). "CXCL10, which is a ligand of CXCR3, is mainly secreted by monocytes, endothelial cells, fibroblasts, and cancer cells." (PMID 34504204, 2021). "Regulates cancer cells' survival, growth, and invasion through producing tissue remodeling molecules, including MMP-2, 9, TNF-α, CXCL10, and IL-1β.Protects cancer cells from cytotoxic effects of radiotherapy and anticancer agents." (PMID 35096289, 2021). "CAF produce numerous factors acting on cancer cells to promote glycolytic metabolism, proliferation, invasion, angiogenesis and metastatic colonisation, including CCL5, CXCL10, IL‐6, TGFα, SDF and versican." (PMID 34841720, 2021). "ESCC tissues and mucosal tissues (5 cm from cancer tissues) were collected, in which HDAC2, miR-503-5p and CXCL10 expression levels were tested." (PMID 33926524, 2021). "CXCL10, CXCL8, CXCL2, and CXCL3 can also induce cell growth and proliferation and are putative autocrine or paracrine growth factors in cancer." (PMID 33939688, 2021). "Oncologically, CXCL10, with its receptor C-X-C motif chemokine receptor 3 (CXCR3), facilitates cancer cell proliferation, metastasis, and invasion." (PMID 33990548, 2021). "As a result, CXCL10, IGF1, MMP3, MMP1, ICAM1, and IL-13 levels were markedly up-regulated within NPC samples relative to the non-carcinoma samples (P < 0.05)." (PMID 34544905, 2021). "CXCL10 and its receptor CXCR3 are increasingly being recognized as pro-tumorigenic in several types of cancers." (PMID 32245422, 2020). "While CCL2, CXCL10, and CX3CL1/CX3CR1 can serve as favorable or unfavorable prognostic factors depending on the cancer types, CCL14 and XCL1 possess good prognostic value." (PMID 31991604, 2020). "CCL2, CXCL10, and CX3CL1/CX3CR1 can serve as both favorable and unfavorable prognostic factors for cancers depending on cancer types." (PMID 31991604, 2020).
cancer (continued). "On the other hand, RNA-seq and Q-PCR analysis showed that TILRR potentiates CXCL10 and CXCL11 chemokine expression in the BT474 cancer cell line." (PMID 33031059, 2020). "AIRE stimulates the expression of the cancer-related proinflammatory genes MMP9, CXCL10, and CXCL11." (PMID 32012175, 2020). "CXCR3 has been identified as a crucial receptor for NK chemotaxis in response to cancer-secreted ligands, CXCL9, CXCL10, and CXCL11." (PMID 32546200, 2020). "We recently reported IL-5, IL-10, IL-6, CxCL-10, and TGF-β elevation in both participants with EpKS and EnKS when compared to KSHV-infected asymptomatic controls prior to cancer therapy." (PMID 32560243, 2020). "Although CXCL10 is only a partial agonist of CXCR3, its impact on many human pathologies including cancer has been extensively studied." (PMID 31216755, 2019). "Similar to CXCL10, CXCL9 is one of the most extensively studied CXCR3 chemokines in cancer and also plays a dual role in the TME." (PMID 31216755, 2019). "In contrast, higher secretion of CXCL10 in CRC increased the infiltration of CD8+ T lymphocytes and inhibited the ability of cancer cells to metastasize." (PMID 31216755, 2019). "Of these six genes, we found four to be significantly correlated with CTL levels across nearly all cancer lineages: CXCL9, CXCL10, CCL5, and IL16." (PMID 29615613, 2018). "First, four out of 16 representative DEGs found in all three subtypes of canine MGTs have strong references in human cancer as biomarkers: CCL23, CXCL10, SFRP2, and FRZB." (PMID 30205506, 2018). "The IFN-γ/CXCL9, CXCL-10, CXCL-11/CXCR3 axis can be a double-edged sword in cancer, promoting an anti-tumor effect but also increasing the capability of cancer cell proliferation, angiogenesis and metastasis." (PMID 30631766, 2018). "Other models propose blockade of immune cell homing to cancer tissue by barrier molecules, chemo-inhibitory mechanisms, and by epigenetic silencing of chemokines (CCL5, CXCL9, and CXCL10), Th1 signaling molecules and antigen processing machinery components." (PMID 29871670, 2018). "Detailed researches on the functions of CXCL12‐CXCR4/CXCR7 pathways and their cross‐talks with CXCR3, CXCL11, CXCL10, and CXCL9 remain urgently warranted, which help lead to safer and more efficient use of their molecular inhibitors in targeted cancer therapy." (PMID 28544785, 2017). "Among them, CXCL10, CXCL11 and CCL11 are chemokines that direct cell migration in development, immunity, inflammation and cancer." (PMID 28938587, 2017). "Of note, CXCL10 and CXCL11 expression was significantly reduced in matched samples from colorectal liver metastasis as compared to primary cancer (n=11)." (PMID 29163806, 2017). "These genetic alterations activate, in a RAS-BRAF-MAPK-dependent manner, transcription of proinflammatory molecules like VEGF-A, CXCL1/GRO-α, CXCL10/IP-10, and CXCL8/IL-8, which can act autocrinously or paracrinously to support cancer cell growth and survival." (PMID 27213120, 2016). "The CXCL10 protein and its receptor (CXCR3) have been proposed as therapeutic targets in cancer and in immune-mediated diseases." (PMID 26222498, 2015). "This review provides an in-depth look into the concepts and mechanisms underlying CALR exposure, activation of the Toll-like receptor 3/IFN/CXCL10 axis, and the release of ATP and HMGB1 from dying cancer cells." (PMID 26486085, 2015). "These cells were exposed to microenvironmental pressures, and the expression of a cancer-related chemokine cluster was used as readout for the malignancy potential (CCL2, CCL5, CXCL8, CXCL10)." (PMID 24213226, 2012). "IFN-γ-inducible protein-10 (IP-10, CXCL10) is one of the CXC chemokines which plays multiple roles in inflammatory diseases and cancer." (PMID 22022583, 2011). "Finally, the promising therapeutic potential of targeting specific chemokine signaling axes, such as CCL2/CCR2 and CXCL10/CXCR3, was discussed as a strategy to improve the efficacy of cancer immunotherapy." (PMID 41635851, 2026).
cancer (continued). "Furthermore, the expression of NKG2D ligand MICB (Fig. EV8F,G) and chemokines CXCL10 and CCL27 (Fig. EV8H) was increased following treatment of cancer cells with BRD4770." (PMID 41366520, 2026). "Pan-cancer analysis of the relationship between OBSCN expression and chemokines revealed a significant negative correlation between OBSCN expression and a variety of chemokines, including CXCL10, CXCL11, CCL11, CCL21, and CCL23." (PMID 40149008, 2025). "The identification of shared DEGs such as CXCL10 and IL6 invites further investigation into their mechanistic roles, building on studies that have underscored the importance of chemokines in immune regulation and cancer progression." (PMID 40063597, 2025). "Notably, CXCL10 and CXCR3 were favourable prognostic factors for cancer patients, and closely related with immune cells infiltration." (PMID 39219056, 2025). "Additionally, in EGFR-TKI resistant cancer cells, upregulation of miR-21 reduces expression of CCL5, CXCL10, IL-6, IL-8, and TNF-α." (PMID 40058234, 2025). "Furthermore, IFN-γ regulates the expression and secretion of CXCL9, CXCL10, and CXCL11, along with their cognate receptor CXCR3 in various immune cells such as T cells, NK cells, monocytes, DCs, and cancer cells." (PMID 40040705, 2025). "Importantly, the C-X-C motif chemokine ligands CXCL9, CXCL10, and CXCL11 were significantly up-regulated in patients with high MOTIscores in both cancer types, suggesting the presence and activation of immune cells in these tumors." (PMID 41463470, 2025). "Notably, in the TCGA pan‐cancer database, samples exhibiting low KDM4B expression displayed elevated levels of IFN‐β, CXCL10, ISG15, PD‐L1 and PD‐1, in contrast to those with high KDM4B expression." (PMID 38390756, 2024). "Moreover, we observed a similar effect of JIB‐04 on the expression of the downstream signalling genes (Cxcl10, Isg15 and antigen presentation‐related genes) of IFN‐β in both human and mouse cancer cells." (PMID 38390756, 2024). "To validate this hypothesis, we treated various cancer cell lines with TH1579 and observed a significant increase in the mRNA expression of the chemokines CCL5 and CXCL10 in NTUB1 and UMUC3 cells at 0.5 μM, and in A549 cells at 1 μM." (PMID 38796460, 2024). "Accordingly, boiled CM did not enhance CXCL10 production in cancer cell monocultures, demonstrating that functional factors derived from immune cells allow cancer cell-intrinsic STING pathway activation by STINGa treatment." (PMID 38992037, 2024). "In addition to CXCL12, there are other chemokines that hold promise for regulating the migration of cancer cells, such as CXCL8, CXCL16, CCL2, and CXCL10." (PMID 39715221, 2024). "In the cancer immune cycle, CXCL10 promotes T-cell trafficking to tumors, whereas it does not promote T-cell infiltration associated with CD8+ TIL density." (PMID 39235457, 2024). "In particular, chemokines, including CXCL8, CXCL10, CXCL11, CXCL16, CCL26, and CCL7, as well as chemokine receptors, including CXCR3, CCR2, CCR5, and CCR1, were positively correlated with MRPL13 expression in various cancer types." (PMID 37827692, 2023). "As a consequence, the predictive ability of CXCL10 and LAMP3 expression was sensible, illustrating the interplay between immunity and cancer, which could better reflect the therapeutic responsiveness in MIBC patients." (PMID 37082269, 2023). "Thus, CXCL10 attracts effector lymphocytes to tumors and can be used as a therapeutic agent in CRC as well as in many cancer models." (PMID 37503314, 2023). "Our experiments in vitro confirmed the ability of poly(I:C)+R848-prot-NCs, with or without HA-mannose coating, to stimulate macrophages towards an M1-like antitumoral mode, characterized by secretion of CXCL10 and CCL5 and also increased cytotoxic activity towards cancer cells." (PMID 38259462, 2023).